RORB (RAR related orphan receptor B)
Diseases named in the same sentence as RORB in open-access papers (continued):
Sharing a sentence is not in itself a finding about the gene and the disease.
Intellectual disability (5 papers, 2015 to 2025). "RORβ variants in patients are associated with susceptibility to various neurodevelopmental conditions, primarily generalized epilepsies, but including intellectual disability, bipolar, and autism spectrum disorders." (PMID 37300435, 2023). "A recent report describes a neurodevelopmental clinical phenotype associated with a de novo RORB SNV in a patient affected by intellectual disability, attention deficit hyperactivity disorder (ADHD), and eyelid myoclonia with absences." (PMID 34768579, 2021). "The patient has a deletion of 582 Kb on 9q21.13 only encompassing exon 1 of RORB, with symptoms of childhood absence epilepsy, intellectual disability, and behavioral problems with aggressive features." (PMID 40692708, 2025). "Observing the frequencies of the characteristics in Group 2A and in Group 3, intellectual disability, autistic behaviour, and seizure are the most specific findings of the involvement of RORB and TRPM6 in 9q21.13 microdeletion syndrome." (PMID 37239476, 2023).
lung carcinoma (5 papers, 2018 to 2025). "Previous studies showed that circadian rhythm-related factors such as the ARNTL, CLOCK, RORA, RORB, CRY1, CRY2, and PER3 genes were associated with a higher risk of lung cancer." (PMID 36385012, 2022). "RORβ is mainly expressed in the central nervous system, but it has also been studied in pharyngeal cancer, uterine leiomyosarcoma, and colorectal cancer, in addition to neuroblastoma, and recent studies suggest that RORγ is involved in various cancers, including lymphoma, melanoma, and lung cancer." (PMID 29904382, 2018).
prostate carcinoma (5 papers, 2017 to 2025). A carcinoma that arises from epithelial cells of the prostate gland. "In particular, the results of our PCR-array suggested that CTCF suppresses the expression of RORB and TIMP3, which are genes that inhibit metastasis in prostate cancer and breast ductal cancer." (PMID 28977939, 2017).
Alzheimer disease (4 papers, 2021 to 2025). A progressive, neurodegenerative disease characterized by loss of function and death of nerve cells in several areas of the brain leading to loss of cognitive function such as memory and language. "Early expression of intraneuronal amyloid-β (not phospho-tau) and inflammatory and glycosylation pathway transcripts distinguish neocortical RORB+ and GAD1+ neurons selectively vulnerable to neurodegeneration in Alzheimer’s disease." (PMID 40467545, 2025).
autism spectrum disorder (4 papers, 2017 to 2024). A spectrum of developmental disorders that includes autism, and Asperger syndrome. "RORβ variants may also confer risk to autism spectrum disorder." (PMID 37300435, 2023). "Most patients with pathogenic RORB mutations exhibit epileptic seizures, while some present with autism spectrum disorder and severe disruption of sleep patterns without seizures." (PMID 39897619, 2024).
colorectal cancer (4 papers, 2017 to 2021). A primary or metastatic malignant neoplasm that affects the colon or rectum. "In recent research, RORβ was a key target through which nuclear receptor-interacting protein 2 (NRIP2) regulated activity of the Wnt pathway in enriched colorectal cancer cells." (PMID 33336001, 2020). "RORβ is upregulated or downregulated in cancers such as primary leiomyosarcoma of the uterus, a pharyngeal cancer cell line, and colorectal cancer." (PMID 29904382, 2018). "We found that RORB was expressed in colorectal cancer cells, but at a lower level in colorectal cancer tissue than in matched para-carcinoma tissues." (PMID 28137278, 2017). "To confirm that RORβ is expressed in intestinal epithelial tissue, we evaluated RORβ expression in colorectal cancer cells by RT-qPCR and western blotting." (PMID 28137278, 2017). "We also examined RORB mRNA expression in primary colorectal cancer tissues by RT-qPCR and mRNA FISH." (PMID 28137278, 2017). "The results showed that the tumorigenic capacity was significantly reduced, the sphere-forming efficiency was decreased and the ratio of CD44+CD24+ cells and the number of colospheres were also obviously reduced in colorectal cancer cells after overexpression of RORβ." (PMID 28137278, 2017). "Immunostaining of RORβ was also carried out in human primary colorectal cancer tissues." (PMID 28137278, 2017). "Moreover, Wen’s study showed that RORB is down-regulated in colorectal cancer." (PMID 33345275, 2021).
generalized epilepsy (4 papers, 2019 to 2024). Epilepsy that is characterized by generalized seizure types and may have typical interictal and/or ictal EEG findings that accompany generalized seizure types (for example generalized spike-wave). "Recently, RORB has also been identified as a novel potential gene involved in human neurodevelopmental disorders, including generalized epilepsy and absence seizures." (PMID 39897619, 2024). "Recently, RORB has also emerged as a novel potential gene involved in generalized epilepsy and absence seizures." (PMID 39897619, 2024). "The authors conclude their report stating that the functional role of RORB perfectly fits with the observed phenotype: generalized epilepsy as well as ADHD, which both involve a wide dysfunction of cortical and subcortical areas rather than a focal brain impairment." (PMID 34768579, 2021). "In our cohort, three patients carried deletions including RORB and exhibited ID and generalized epilepsy, including absence seizures with eyelid myoclonia, and autistic features in one patient, supporting a role for RORB in GGE and, more broadly, in several neurodevelopmental disorders." (PMID 30866059, 2019).
glioma (4 papers, 2011 to 2025). A benign or malignant brain and spinal cord tumor that arises from glial cells (astrocytes, oligodendrocytes, ependymal cells). "The researchers studied the impact of CCGs in the development of lower grade glioma and observed that certain genes including RORβ, NPAS2, and CRY1 were linked with elevated or reduced risk of lower grade glioma." (PMID 40495887, 2025). "RORα and RORβ, which modulate the transcription of Bmal1, were observed to be downregulated in gliomas, and this expression profile was prognostic in a cohort of glioma-diagnosed patients suggesting that its function is associated with tumor genesis and progression." (PMID 34361055, 2021). "On the other hand, 10 genes showed 0- to 2-fold decrease, 6 genes showed 2- to 10-fold decrease and RORβ, SF1 and PNR showed more than 10-fold decrease in BTSCs compared with glioma." (PMID 21224854, 2011).
neuroblastoma (3 papers, 2018 to 2025). Neuroblastoma (NB) is the most common solid, extracranial childhood tumor. "Our results showed that RORβ is highly expressed in the SH-SY5Y neuroblastoma cell line, compared to RORα and RORγ isoforms." (PMID 39105871, 2025). "The natural expression of RORβ is exclusively restricted to neuronal tissues; therefore, activation of RORβ transcription is predominantly found in neuroblastoma cell lines, and literature on the role of RORβ in cancer is not much." (PMID 29904382, 2018). "Immunohistochemistry indicated that when compared with ganglion cell neuroblastoma (GNB), lower immunostaining of RORB was concomitant with elevated RBM10 expression in NB tissues." (PMID 40899609, 2025).
retinal degeneration (3 papers, 2021 to 2025). Degeneration of the retina. "In a previous study, RORβ-deficient mice exhibited retinal degeneration, indicating the role of RORβ in the development of the retina." (PMID 33669807, 2021). "This study demonstrated that siRNA-mediated knockdown of RORB preserves rod photoreceptor survival and attenuates retinal degeneration in RhoP23H mice." (PMID 41153677, 2025).
leiomyosarcoma (2 papers, 2015 to 2018). An uncommon, aggressive malignant smooth muscle neoplasm, usually occurring in post-menopausal women. "With respect to RORβ and cancer, a recent study reported that RORB is overexpressed in primary leiomyosarcomas, the most common type of uterine sarcoma." (PMID 26878025, 2015).
mood disorder (2 papers, 2013 to 2022). A cognitive disorder a disturbance in which the person's mood is hypothesized to be the main underlying feature. "Findings from the targeted examination of clock genes revealed several significant associations with depression (NR1D1 and PER1) and BIP-I (ARNTL, CRY2, RORB) underlining the close relationship with mood disorders." (PMID 36131119, 2022).
retinitis pigmentosa (2 papers, 2023 to 2025). Retinitis pigmentosa (RP) is an inherited retinal dystrophy leading to progressive loss of the photoreceptors and retinal pigment epithelium and resulting in blindness usually after several decades. "NRL mutations have been associated with retinitis pigmentosa and mutations in Blimp-1, RORβ, Otx2, Crx, or Nrl are associated with a loss of rod PRs in mammals." (PMID 36960411, 2023).
adrenal hypoplasia (1 paper, 2015). "Included in this group were AR, Coup-TFα, Coup-TFβ, dosage-sensitive sex reversal-adrenal hypoplasia congenital critical region on the X chromosome, gene 1 (DAX1), ERα, ERRα, HNF4γ, liver receptor homolog-1 (LRH1), NOR1, NURR1, PPARγ, RARβ, RORα, RORβ, and VDR." (PMID 26244663, 2015).
aging (1 paper, 2017). A developmental process that is a deterioration and loss of function over time. "Our data showed associations between cognitive aging and single nucleotide polymorphisms (SNPs) in 4 key circadian clock genes, CLOCK rs3749473 (p = 0.0017), NPAS2 rs17655330 (p = 0.0013), RORA rs13329238 (p = 0.0009), and RORB rs10781247 (p = 7.9 × 10−5)." (PMID 28412756, 2017).
asthma (1 paper, 2025). "Consistent with our previous research demonstrating reduced clock protein oscillation in monocytes from mild asthmatics, diminished clock protein levels, including decreased morning REV ERBα and RORβ expression, were detected in monocyte subsets of the moderate asthma cohort." (PMID 40131242, 2025).
atherosclerosis (1 paper, 2021). A disease characterized by the build-up of fatty material and calcium deposition in the arterial wall resulting in partial or complete occlusion of the arterial lumen. "In this study, we revealed that RORB, RORC, PER1, CRY1, FTO were in close relationship with atherosclerosis, particularly in atherosclerotic lesions with higher immune infiltration." (PMID 34082770, 2021). "All the available evidence suggests that chronopharmacology-based therapy targeting RORB, RORC, PER1, CRY1, or FTO might constitute another approach for the treatment of atherosclerosis." (PMID 34082770, 2021).
buccal mucosa cancer (1 paper, 2025). "In addition to the RORB SNP rs10781247 variants, a significantly higher distribution frequency of RORB SNP rs3750420 variants was observed in patients with buccal mucosa cancer and a higher tumor T status compared with individuals with tongue cancer." (PMID 39744492, 2025). "Moreover, RORB SNP rs3750420 variants were significantly associated with larger tumor size in individuals with buccal mucosa cancer (AOR: 1.542, 95% CI: 1.027 to 2.315, p = 0.036)." (PMID 39744492, 2025). "We speculated that the RORB SNP rs3750420 variants interact with genes involved in the development of buccal mucosa cancer, thereby influencing the clinical characteristics of this cancer type." (PMID 39744492, 2025). "Moreover, variants of the RORB SNP rs3750420 were associated with a higher tumor T status in patients with buccal mucosa cancer." (PMID 39744492, 2025).
cardiac hypertrophy (1 paper, 2021). "Moreover, RORα and RORβ, nuclear MLT receptors, are involved in MLT-mediated regulation of pathological and physiological cardiac hypertrophy." (PMID 34899707, 2021).
cholangiocarcinoma (1 paper, 2025). A carcinoma that arises from the intrahepatic biliary tree (intrahepatic cholangiocarcinoma) or from the junction, or adjacent to the junction, of the right and left hepatic ducts (hilar cholangiocarcinoma). "Our analysis revealed that RORC amplification and elevated mRNA levels were detected in 20% of cholangiocarcinoma cases, compared to other members of the ROR family, including RORA and RORB." (PMID 41430037, 2025).
Cognitive impairment (1 paper, 2017). Abnormal cognition is characterized by deficits in thinking, reasoning, or remembering. "As a result, four SNPs, including the RORA-rs13329238, NPAS2-rs17655330, CLOCK-rs3749473, and RORB-rs10781247 SNPs individually and interactively alters the hazard of cognitive deficits in terms of MMSE scores for normal aging." (PMID 29209239, 2017).
cutaneous melanoma (1 paper, 2023). A primary melanoma arising from atypical melanocytes in the skin. "According to the cBioPortal and TIMER 2.0 database, the most mutated circadian genes among cutaneous melanoma patients were PER1, PER2, RORB and RORC." (PMID 37373286, 2023).
dementia (1 paper, 2025). Loss of intellectual abilities interfering with an individual's social and occupational functions. "Whilst RORB layer 4 excitatory neurons may play a differential role in dementia in LBD, we also found important similarities between the drivers of gradient differences in LBD and PD-NC." (PMID 41290734, 2025).
endometriosis (1 paper, 2022). The growth of functional endometrial tissue in anatomic sites outside the uterine body. "AEBP1 and KLF2 were higher expressed, while DLX6, HOXB6, and RORB were lower expressed in endometriosis in the GSE7305 dataset." (PMID 36532015, 2022). "Our analyses point to, HOXB6, KLF2, and RORB, maybe cross-regulatory genes in endometriosis and SLE." (PMID 36532015, 2022). "Our results showed that HOXB1, AEBP1, and RORB were involved in endometriosis and SLE." (PMID 36532015, 2022). "AEBP1, HOXB6, KLF2, and RORB may be potential biomarkers for endometriosis." (PMID 36532015, 2022). "NEAT1 and XIST may regulate the expression of four TFs (AEBP1, HOXB6, RORB, and KLF2) through the lncRNA-miRNA-mRNA network and participate in the development of endometriosis." (PMID 36532015, 2022). "The roles of KLF2 and RORB in endometriosis have not been explored." (PMID 36532015, 2022).
epileptic seizures (1 paper, 2025). "As is known, the RORB gene is associated with susceptibility to idiopathic generalized epilepsy-15 (EIG15; OMIM #618357), an autosomal dominant disease with possible incomplete penetrance which is characterized by the occurrence of different types of epileptic seizures within the first decade." (PMID 40692708, 2025).
gastric cancer (1 paper, 2022). A primary or metastatic malignant neoplasm involving the stomach. "RORB can down-regulate the activity of Wnt signaling pathway, thus inhibiting the stemness of gastric cancer cells." (PMID 36311731, 2022).
head and neck squamous cell carcinoma (1 paper, 2025). A squamous cell carcinoma that arises from any of the following anatomic sites: lip and oral cavity, nasal cavity, paranasal sinuses, pharynx, larynx, and salivary glands. "An analysis of Cancer Genome Atlas data revealed that RORB mRNA levels were significantly higher in patients with head and neck squamous cell carcinoma compared with controls (p = 0.0002)." (PMID 39744492, 2025). "Moreover, RORB mRNA expression was highest in stage IV head and neck squamous cell carcinoma and lowest in stage I head and neck squamous cell carcinoma." (PMID 39744492, 2025). "Furthermore, RORB mRNA levels were significantly higher in patients with head and neck squamous cell carcinoma, with the highest expression levels observed in those with advanced tumor stages." (PMID 39744492, 2025). "Furthermore, the RORB mRNA expression levels were significantly higher in patients with head and neck squamous cell carcinoma, particularly in those with advanced tumor stages." (PMID 39744492, 2025). "In the bioinformatics analysis using the Cancer Genome Atlas database, individuals with head and neck squamous cell carcinoma exhibited significantly higher RORB mRNA expression compared with noncancerous tissues." (PMID 39744492, 2025). "Analysis of Cancer Genome Atlas data revealed that RORB mRNA levels were significantly higher in patients with head and neck squamous cell carcinoma than in those with noncancerous tissues (p = 0.0002)." (PMID 39744492, 2025).
intestinal tumors (1 paper, 2017). "We detected RORβ expression in normal intestinal epithelial cells and intestinal tumors; moreover, RORB was also decreased in cancer tissues, suggesting that the distribution of RORβ may be more widespread than is currently known and that RORβ may play a role as a tumor suppressor." (PMID 28137278, 2017).
Jeavons syndrome (1 paper, 2025).
osteoporosis (1 paper, 2023). A condition of reduced bone mass, with decreased cortical thickness and a decrease in the number and size of the trabeculae of cancellous bone (but normal chemical composition), resulting in increased fracture incidence. "In addition, RORβ has been identified as a molecular target of miR-219a-5p in recent years, which is involved in the development of osteoporosis." (PMID 38027103, 2023).
pancreatic cancer (1 paper, 2017). "Recently, RORβ was detected in tissues outside of the nervous system, such as normal bone tissue, the endometrium and pancreatic cancer." (PMID 28137278, 2017).
preeclampsia (1 paper, 2024). Preeclampsia is a hypertensive disorder of pregnancy that is characterized by new-onset hypertension with proteinuria presenting after 20 weeks of gestation, and depending on mild or severe forms may initially present with severe headache, visual disturbances, and hyperreflexia. "These include decidualization markers such as PRLR and IGFBP3, as well as genes that have previously been reported to have roles in trophoblast invasion, such as FERMT2 and RORB, for which expression changes in preeclampsia have been observed in fetal placenta." (PMID 39090334, 2024). "These predicted targets included classical decidualization-inducing genes as well as genes previously reported to have preeclampsia-related transcriptional changes in trophoblasts, such as FERMT2 and RORB." (PMID 39090334, 2024).
Sepsis (1 paper, 2023). Sepsis is defined as life-threatening organ dysfunction caused by a dysregulated host response to infection. "We found a decreased mRNA level in cardiac nuclear RORα but not RORβ/γ or MT1/MT2 in both sepsis models, which was further confirmed by western blotting and immunohistochemical assays." (PMID 37147703, 2023).
sleep disorder (1 paper, 2022). A change from the patient's baseline sleeping pattern, in the hours slept and/or an alteration/dysfunction in the stages of sleep. "A total deletion of RORβ in mice causes sleep disorder, hindlimb motor control, opsin induction in cone photoreceptors and differentiation of rod photoreceptors." (PMID 36080415, 2022).
temporal lobe epilepsy (1 paper, 2023). A localization-related (focal) form of epilepsy characterized by recurrent seizures that arise from foci within the temporal lobe, most commonly from its mesial aspect. "RORB (RAR-related orphan receptor β) is expressed in the temporal cortex, as demonstrated on cortical samples from patients with temporal lobe epilepsy and in rat brains and it probably has a role in neuronal cell differentiation." (PMID 37239476, 2023).